IL1B (interleukin 1 beta)
Diseases named in the same sentence as IL1B in open-access papers (continued):
Sharing a sentence is not in itself a finding about the gene and the disease.
tumor (continued). "Cytokines, chemokines, and growth factors such as IL-6, IL-8, IL-1β, TNF-α, TGF-β, GM-CSF, VEGF, and angiopoietins have been shown to promote angiogenesis and tumor metastasis." (PMID 29541344, 2018). "We further detected 20 serum cytokines in tumor-bearing mice and 7 cytokines were significantly different between GLE treated and model groups, including IFN-γ, IL-1β, IL-4, IL-9, IL-12, RANTES and TNF-α." (PMID 30139984, 2018). "We observed up-regulation (more than 2 standard deviations) of number of pro-inflammatory cytokines (G-CSF, GM-CSF, IFN-γ, IL-1β, IL-17, TREM-1, TNF) in mice with three-week tumors as compared to one-week tumor." (PMID 30323345, 2018). "We used multiplex ELISA to demonstrate the presence of IL1B, IL6, IL8, IL10, IL18, TNF and IFNG in the cystic fluid and whole ACP tumour protein lysates." (PMID 29541918, 2018). "HNSCC can induce the production of active IL-1β through NLRP3 inflammasome pathways, and inhibition of the NLRP3 inflammasome pathway was suggested to be a promising approach for decreasing tumour cell invasion and survival." (PMID 30447690, 2018). "In the early angiogenic response during tumor development, cross talk between VEGF and IL-1β takes place." (PMID 30042333, 2018). "Although the most commonly studied cytokines regulated by MK2 are IL-1β, IL-6, and TNF-α, here we showed that MMM are also substantially decreased in tumor cells and in tumors with mixed cell populations upon MK2 inhibition." (PMID 30298062, 2018). "Antibiotic-induced dysbiosis in mice model promotes intestinal inflammation and thus produce higher levels of pro-inflammatory cytokines including tumor TNF-α, IL-1β, MCP-1, and IFN-γ." (PMID 30065236, 2018). "For example, non-tumor cell-derived TNF-α, IL-6, IL-8, and IL-1β stimulate tumor cell proliferation, invasion, and metastasis via paracrine signaling." (PMID 30038719, 2018). "Our previous studies indicated that the MK2 pathway regulates IL-1β, IL-6, and TNF-α in CRC tumor models." (PMID 30298062, 2018). "IL-1β is also known to enhance the production of IL-17 by CD4+ T cells, which in turn favors angiogenesis and tumor growth." (PMID 30631327, 2018). "This was accompanied by the production of IFN-γ, interleukin-β (IL-1β) and TNF-α inhibiting tumor growth." (PMID 29466981, 2018). "Tumor-derived Jagged, in turn, boosts the expression of IL-1β and CCL2 in the same tumor cells and in TAMs." (PMID 30154786, 2018). "For example, tumor secreted factors, including lactate and HMGB1, induced macrophage polarization to M2 type, but these factors also induced IL-1β production in the cells." (PMID 30586442, 2018). "CX3CL1 is a chemokine induced by inflammatory cytokines such as TNFα, IL-1β, and IFN-γ and its role is to recruit immune cells at tumor sites and to boost antitumor immune responses." (PMID 30108590, 2018). "IL-1β induces CCL2 expression in TAM and tumor cells as well, regulating myeloid cell recruitment into tumor tissue." (PMID 30042333, 2018). "We also found that residual tumor-promoting activity in skin of TNF−/− mice was induced by IL-1α and IL-1β gene expression." (PMID 30341686, 2018). "Recent studies have attributed tumor suppression by ΔppGpp Salmonella to a marked increase in production of proinflammatory cytokines, namely, TNF-a and IL-1b, by macrophages and dendritic cells infiltrated into the tumor mass." (PMID 29492216, 2018). "Src can increase pro-inflammatory cytokines production for tumor development and activate survival effectors for chemoresistance, including TNF-α, IL-1β, IL6, phosphoinositide 3-kinases (PI3Ks), AKT and STAT3." (PMID 30473665, 2018). "Tumour‐derived mediators, such as TGF‐β, IL‐1β and IL‐6, as well as cytokines produced by T cells, such as IFN‐γ, IL‐4 and IL‐10, promote MDSCs population expansion and support their immunosuppressive activity." (PMID 28276625, 2017).
tumor (continued). "Employing this approach, they recognized a core of nine cytokines that consistently correlated with efficacious tumour suppression: IL-12p70, IFN-γ, IL-1α, IL-1β, IL-2, IL-3, IL-6, CXCL10, and CXCL9." (PMID 29089667, 2017). "Target genes of glucose-induced H3 ubiquitination, such as interleukin (IL)-1α, IL1β and glutamate-cysteine ligase regulatory subunit (GCLM), are also important factors for tumour sphere formation." (PMID 28300060, 2017). "SAMP colonic organ-cultured tumor biopsies showed increased levels of IFN-γ and IL-1β compared to AKR mice." (PMID 28301579, 2017). "According to the RT-PCR and ELISA results, the tumor group exhibited significantly higher levels of TNF-α and IL-1β in spinal cord and serum compared with sham group (p < 0.01)." (PMID 28587280, 2017). "IL-1β and KC/GRO were found in both xenografts and non-tumour bearing NOD-scid, whereas IL-6 and TNF-α were exclusively detected in xenograft tissue." (PMID 28417956, 2017). "Upon arriving at the tumor site, they release IL-1β and tumor necrosis factor-α (TNF-α) to achieve anti-tumor effects." (PMID 28753959, 2017). "Functionally, we show that NEDD4-mediated H3 ubiquitination, by transcriptionally activating IL1α, IL1β and GCLM, is important for tumour sphere formation." (PMID 28300060, 2017). "Aggregation of T-cells and APCs will induce the formation of inflammasomes, which promote IL-1β secretion and activation of CD8+ T-cells, eventually leading to cell-mediated anti-tumor immune responses." (PMID 28753959, 2017). "RT further affects the tumor microenvironment by inducing increased expression of pro-inflammatory cytokines, such as TNF-α, IFN-γ, IL-1β, IL-6 and IL-12, type-I interferons and chemokines, which stimulate infiltration of immune cells into the tumor." (PMID 28233730, 2017). "In addition to adhesion and transmigration, stimulation of both MDA-MB-231 and MCF7 tumour cells with IL-1β increased their migratory ability; furthermore, this increase was also observed with macrophage conditioned media and could be inhibited with a caspase-1 inhibitor." (PMID 28551814, 2017). "Remarkably, co-administration of NAC and IL1β completely rescued the defect in tumour sphere formation upon NEDD4 knockdown, suggesting both IL1β and anti-oxidant are critical for tumour sphere formation." (PMID 28300060, 2017). "Inflammatory cytokine generation is a critical process in the regulation of inflammation and the advancement of tumours, and this study's findings corroborate CIE's capacity to inhibit TNF-α and IL-1β." (PMID 28491105, 2017). "In fact, the tumor microenvironment secretes many factors such as GM-CSF, VEGF, SCF, IL-6, IL-10, IL1β, PGE2, cyclooxygenase enzyme (COX) and the complement component C5a which promote recruitment and accumulation of immature MDSCs." (PMID 28609459, 2017). "It is interesting that while IL-1β, CCL2, and VEGF are secreted at high levels from hypoxic and/or MSCs-entrained IRISOE TNBC tumor cells, their receptors, IL-1R, CCR2, and VEGFR2 were only observed on MSCs, TAMs, and ECs, respectively." (PMID 29262555, 2017). "On the opposite, soluble factors present in the tumor microenvironment such as TGF-β, TNF-α, IL1β and FGF promote the expression of MMPs by fibroblasts." (PMID 28423623, 2017). "BAX69 abrogates MIF signaling and MIF-mediated secretion of cytokines (IL-1β, TNF-α, etc.)and inhibits proliferation of MIF overexpressing tumor cells, together with the antiproliferative effects of panitumumab (anti-EGFR mAb)." (PMID 29312320, 2017). "A tumour metastasis PCR array showed that the expressions of many genes (ECADHERIN, NME4, SYK, CD44 and IL1B) were changed in NPC cells with HOPX overexpression." (PMID 28146149, 2017). "The expression of immunoinhibitory molecules and cytokines, for example, IL-1β, VEGF, IL-10, and TGFβ and downregulation of immunostimulatory cytokines (e.g., IL-2, IL-12, IL-15) allow tumor to escape from immune control." (PMID 28052005, 2017).
tumor (continued). "Studies have shown that IL1B and the p38 and p42/44 MAPK pathways play important roles in tumor cell progression." (PMID 28143606, 2017). "Similar to tumour antigen-specific CTL-mediated antitumour immunity, we found that MLR antigen-specific CTLs activated NLRP3 inflammasome for IL-1β production in APCs, and the CTL-mediated GVHD induced IL-1β production through NLRP3 inflammasome." (PMID 28537251, 2017). "Together suggest that while IRISOE tumor cells secrete low-level CCL2 under normal condition, hypoxia and/or MSCs contact through the IL-1β/CXCL1 circuit exacerbates CCL2 secretion from these cells." (PMID 29262555, 2017). "Mechanistically, our findings argue that expression of MMP9 in tumor cellsis regulated by crosstalk of TGF-β with TNF and/or IL-1β cytokines." (PMID 28423685, 2017). "Therefore, we analysed CTL populations in the tumours and found that effector memory CTLs were the majority of the population and had the highest expression of perforin and granzyme B, suggesting that effector memory CTLs are critical for IL-1β secretion in the tumour model." (PMID 28537251, 2017). "To test the importance of IL-1β–mediated stromal signals in conferring tolerance to MAPK inhibition in vivo, we again injected 4434 into Il-1r1fl/fl and Il-1r1−/− mice and analyzed tumor growth in the presence of MEKi." (PMID 28450382, 2017). "MDSCs are recruited and regulated by multiple inflammatory mediators such as IL-1β, IL-6, and PGE2, which are released by tumor cells and stromal cells in an autocrine or paracrine fashion." (PMID 28360909, 2017). "Several pro-inflammatory cytokines were found at higher concentrations in the spleen of both flank and orthotopic tumor-bearing groups when compared to sham, including KC (murine IL8 homologue), TNFα, and IL1β." (PMID 27901481, 2017). "We further measured the level of cytokines TNFα, IL-1β, IL-6, IL-17, IL23 and Cox-2 in tumor and normal tissues collected from the mouse colon using RT-qPCR." (PMID 28704539, 2017). "Significant differences of IL-1β, IL-6, TNF-α and HGF were also detected in the comparison between tumor and non tumor HF and LF-HC bearing mice." (PMID 28881825, 2017). "Together suggest that while IRISOE tumor cells secrete low-level VEGF under normal condition, hypoxia and/or MSCs contact through the IL-1β/CXCL1 circuit exacerbates VEGF secretion from these cells." (PMID 29262555, 2017). "Nevertheless, OSCC cells and TAMs together through IL-1β/IL-1R and CXCR4/ SDF-1α and via activation of the ERK signalling pathway produce tumour cell migration and invasion by inducing expression of matrix metalloproteinase (MMP) enzymes MMP-9 and MMP-13." (PMID 28381274, 2017). "Mounting evidence support that both IL-1β and IL-8 promote EMT in tumor cells and induce tumor cells, and other stromal cells, to secrete MMPs." (PMID 28337194, 2017). "The expression pattern of TREM1 was closely paralleled by the expression of IL1B and S100A9 which were also increased in the tumor tissue." (PMID 29093489, 2017). "There was a decrease in the concentration of several soluble mediators in EMT6siCD200 tumor lysates compared with EMT6 lysates, including G-CSF, GM-CSF, IL-1β, MCP-5, MIP-1β, and RANTES." (PMID 28234914, 2017). "Podgorski and colleagues demonstrated that lipids can be trafficked between adipocytes and cancer cells fuelling tumour growth and invasiveness by upregulating FABP4, IL-1β and HMOX-1 in the metastatic tumour cells." (PMID 27761371, 2016). "In particular, the Hes1-mediated suppression of Pparg perpetuates the autocrine inflammatory activity of tumor pancreatic cells, inducing the production of inflammatory mediators, such as TNF- α, IL-6 and IL-1β." (PMID 27929540, 2016). "The mRNA levels of colorectal inflammatory cytokines TNF-α, IL-1β, IL-6, CSF-1, and MCP-1, and COX-2 were increased in tumor and surrounding tissues from AOM/DSS-treated mice." (PMID 27557503, 2016).
tumor (continued). "In conclusion, our data imply lung tumor lesions are populated by macrophages which pro-tumor activity is regulated by the activation of the NLRP3 inflammasome that leads to the release of IL-1α and IL-1β in a caspase-11/caspase-1-dependent manner." (PMID 27528423, 2016). "Our study points to the production of soluble cytokines IL1A, IL1B and IL8, as markers of a poor response to cetuximab and as potential key factors in CRC tumor adaptation to cetuximab pressure." (PMID 27708224, 2016). "Among them, MCP-1 (CCL-2), IL-1b, IL-6, TNF-α were especially shown to be involved in the recruitment of immature cells into tumor microenvironment." (PMID 27993141, 2016). "Immune cells that infiltrate the tumour, excluding NK cells, produce tumour cytokine promoters, such as tumour necrosis factor alpha [TNF-α] and interleukins IL-1β, IL-6, and IL-8, which increase signalling in pre-malignant cells." (PMID 26913068, 2016). "Actors of this inflammatory process, such as tumor-associated macrophages (TAMs) or MDSCs and their secreted cytokines (IL-6, IL-1β, TNF) are now considered as key in promoting tumor progression." (PMID 27713124, 2016). "In accordance with our in vitro data, IL1A, IL1B and IL8 were overexpressed in tumorgrafts that proved to be resistant to EGFR blockade (tumor volume increase of at least 35% compared to the initial, pre-treatment volume)." (PMID 27708224, 2016). "The expression of the molecules, including TNF‐α, IL‐1β, HIF‐1α, NF‐κB, VEGF, and MMP9 in tumor tissues was analyzed by the methods of immunohistochemistry and western blot." (PMID 27734611, 2016). "Under normoxia, MMP1 and integrin (ITGA4) were elevated in TNF-α and TNFα/IL-1β clones; these can degrade the ECM component and play a role in the development of tumour metastasis." (PMID 26759080, 2016). "We next used immunohistochemical (IHC) staining to evaluate the protein expression levels of ASC, IL-1β, CASP1 and NLRP3 in tumor cells using a second cohort of OSCC biopsy samples (n=111)." (PMID 27367024, 2016). "Conversely, TIS-CD8+ T cells promote CD16+ expression in monocytes/macrophages and the production of pro-inflammatory cytokines (TNF, IL-1β, and IL-6) and angiogenic factors (MMP-9, VEGF-A, and IL-8), which can affect tumor progression." (PMID 27129159, 2016). "CCL1 production and tumor cell migration to LECs are also promoted by proinflammatory mediators TNF, IL-1β and lipopolysaccharide." (PMID 28036019, 2016). "Given the recent successes of immune modulators in cancer therapy and the improved understanding of immune evasion by tumours, we sought to determine the carcinogenic impact of chronic TNF-α and IL-1β exposure in a normal bronchial epithelial cell line model." (PMID 26759080, 2016). "Specifically, the chemokine‐related genes, CXCL1, CXCL2, CXCL3, and IL‐1β, were up‐regulated, while CXCR1 was down‐regulated in tumor tissue during the progression of HCC." (PMID 27682863, 2016). "In this study, we identified decreased FSTL1 expression in NPC tissue sections, concomitant with downregulation of IL-1β and TNF-α in tumor tissue macrophages." (PMID 26918942, 2016). "Taken together these data imply that lung tumor lesions are populated by macrophages which pro-tumor activity is regulated by the activation of the NLRP3 inflammasome that leads to the release of IL-1α and IL-1β." (PMID 27528423, 2016). "Inflammatory cell infiltration, fibrous tissue hyperplasia, and tumor-like epithelial proliferation were significantly reduced in the MMUS group, as were the mRNA and protein expressions of TNF-α and IL-1β." (PMID 26797392, 2016). "The findings have shown that protein which includes the likes of Eotaxin, Fas ligand, IGF-II, IL-1β, TNF-α, IL-13, Leptin, and TIMP-1 were decreased when compared to the untreated tumor." (PMID 27558166, 2016). "Several genes were up‐regulated in tumor tissues during the progression period, including CXCL1, CXCL2, CXCL3, and IL‐1β, while CXCR1 expression was down‐regulated." (PMID 27682863, 2016).
tumor (continued). "Our PCR array data showed that both M1-related genes (Ccl2, Ccl3, Ccl4, Ccl5, Il12b, Il1b and Ccl1) and M2-related genes (Il10, Tgfb2 and Il1rn) were significantly upregulated in NM11-shsST2 tumours compared with NM11-shCont tumours." (PMID 27882929, 2016). "Here, we show that the NLRP3 inflammasome-related proteins, ASC, IL-1β, CASP1, and NLRP3, are all highly expressed in OSCC tumor cells compared to adjacent normal cells." (PMID 27367024, 2016). "These multiple lines of evidence support the idea that pro-inflammatory stimuli, such as IL-1β, IL-6, IL-8 and TNF-α can lead to the activation of Notch signaling with a tumor-promoting effect on epithelial cells." (PMID 27929540, 2016). "IL16, produced by CD8+T cells, can stimulate the secretion of tumor-related cytokines, such as TNF-α, IL1β, IL6, and IL1516." (PMID 27703190, 2016). "IL-1β increased stem-cell-like phenotypes, invasiveness, survival in a three-dimensional culture model, and estrogen-independent tumor growth of TG2-expressing MCF7 cells, which was attenuated by either anti-IL-6 or anti-IL-1β antibody treatment." (PMID 27609180, 2016). "IL-1β increases expression of VEGF and its receptors on endothelial cells and acts together with VEGF in promoting tumor mediated angiogenesis." (PMID 26919112, 2016). "We have reported that the augmented expression of IL-1α, IL-1β, VEGF-A and VEGF-C by macrophages promotes tumor growth and tumor angiogenesis/lymphangiogenesis." (PMID 26778110, 2016). "It is well established that pro-inflammatory cytokines and mediators, including IL-1β, IL-6, TNF-α, iNOS and Cox-2 which acts as tumor promoter is tightly modulated by transcription factor NFκB." (PMID 27563884, 2016). "IL-1β was also demonstrated to up-regulate the production of TNF-α by myeloid and/or tumor cells in the tumor microenvironment that significantly activates MDSC immunosuppressive functions." (PMID 27827871, 2016). "Highly expressed inflammatory factors such as IL‐1β and TNF‐α, markers of inflammatory cells such as CD68 and CD11b, and massive inflammatory cells tracked by fluorescence in necrotic tumor tissue were detected in the tumor tissue of this model." (PMID 27734611, 2016). "Proinflammatory cytokine IL-1β and VEGF, produced by TAMs, stimulate MMPs production by tumor cells and angiogenesis, respectively." (PMID 27807511, 2016). "Taken together these data imply that lung tumor lesions are populated by macrophages which pro-tumor activity is regulated by the activation of the NLRP3 inflammasome that leads to the release of IL-1α and IL-1β in a caspase-11/caspase-1-dependent manner." (PMID 27528423, 2016). "Levels of IL-12 remained unchanged in both LLC and B16F10 tumours although B16F10 tumours showed stimulation of all other cytokines evaluated while LLC only showed increased levels of IFNγ and IL-1β compared to untreated controls." (PMID 27412241, 2016). "Levels of IL-6, IL-1β, and tumour necrosis factor-α (TNF-α) in tumour tissue were 6.41−, 1.97−, and 1.83-fold higher in mice treated with HTiO2 NPs and US than in saline-treated control animals." (PMID 26996446, 2016). "The work from the same lab stated that 5-FU also induces activation of NLRP3 in dying MDSC, leading to secretion of IL-1β, elicitation of TH17 cells, IL-17 production and tumor growth following increased angiogenesis." (PMID 27645787, 2016). "IL1β activated the p38 MAPK signaling pathway and expression of monocyte chemoattractant protein (MCP-1/CCL2) by tumor cells." (PMID 25987130, 2015). "The cytokines IL-1β, IL-6, IL-8 and TGF-β play important roles in the development of drug resistance in tumor cells." (PMID 25950430, 2015). "It seems that during tumor development, inflammatory environment (IL1β and IL23) modulate the cytokine profile of γδT cells from primary IFNγ toward proinflammatory IL17, which support tumor progression." (PMID 25699053, 2015).